INS (insulin)
Diseases named in the same sentence as INS in open-access papers (continued):
Sharing a sentence is not in itself a finding about the gene and the disease.
diabetes (continued). "T2DM (formerly known as diabetes without insulin) is the most common diabetes’ form, characterized by hyperglycemia, insulin resistance, and relative insulin deficiency." (PMID 31574903, 2019). "Studies including pregnant women with pre-existing diabetes or non-diabetic women were excluded, as were trials comparing metformin treatment with oral glucose-lowering agents other than insulin." (PMID 31386659, 2019). "Screening DPP-4 inhibitors for treating diabetes is a recently developing field (since 2006), when a study reported that DPP-4 might regulate insulin sensitivity via degradation of GLP-1." (PMID 30691220, 2019). "Patients with all types of diabetes were classified as having non-insulin-dependent or type 2 diabetes, although many eventually required insulin treatment themselves, despite their less aggressive disease course." (PMID 31558146, 2019). "Unfortunately, insulin treatment on STZ diabetes-like mouse was failed to improve body weight and muscle mass, even blood glucose level was significantly reduced." (PMID 31327904, 2019). "Pancreatic autoantibodies and C-peptide did not always predict diabetes subtypes nor respond to insulin." (PMID 30682116, 2019). "Several participants felt that the user interface of the RT-CGM was specific to insulin-requiring diabetes and not to those who are not insulin requiring." (PMID 31313657, 2019). "Diabetes mellitus was diagnosed in 183 (51%) patients, of whom 14% were diet controlled, 70% were on oral antidiabetic drugs and/or injectable GLP1 analogues, and 16% were on insulin treatment." (PMID 30836450, 2019). "Overall, in muscle, adipose tissue, and liver—the major target tissues for insulin—it is not clear how autophagy is affected in T2D, although it would seem to be suppressed when diabetes and insulin resistance are present." (PMID 31487953, 2019). "Here, we aim to determine the relation of differential DNA methylation and fasting glucose and insulin metabolism as markers of early stages of diabetes pathology in non-diabetic subjects, accounting for obesity measured as body mass index (BMI)." (PMID 31197173, 2019). "TXNIP is upregulated in diabetes and a concomitant increase in miR204 expression allows for the increased direct targeting and degradation of MAFA, an established transcription factor for insulin." (PMID 32432227, 2019). "Pharmacologic therapies such as oral medications and insulin, and non-pharmacologic therapies such as lifestyle modifications are still considered contemporary interventions for managing diabetes." (PMID 30794570, 2019). "Although STZ‐induced diabetes resembles to a great extent type 1 diabetes, no requirement for insulin therapy is an important point for cautious interpretation of the results from animal studies and their translation to humans." (PMID 30740930, 2019). "In the present study, diabetes in STZ-induced rats was assessed by a significant increase in the blood glucose level, glycosylated Hb and absolute kidney weight whereas; decrease in serum insulin and body weight." (PMID 30804780, 2019). "Alternatively, functional glucose-responsive, insulin-secreting cells, derived from patients’ own MSC and generated in large numbers by small molecule-aided non-integrative methods, can be a better solution for curing diabetes." (PMID 31547868, 2019). "MCP-1 appears higher in the visceral and subcutaneous adipose tissues of obese patients compared to lean controls, and insulin induces mRNA expression and secretion of MCP-1, therefore, increased MCP-1 in diabetes might be due to adipose tissues secretion." (PMID 30909920, 2019). "Unlike metformin, insulin use as monotherapy or in combination with 1–2 oral anti-diabetic agents by our patients with diabetes was a predictor of poor glycemic control." (PMID 31297092, 2019).
diabetes (continued). "We found no clinically remarkable changes between the groups in diabetes-related variables such as fasting blood glucose, fasting insulin, HbA1c (NGSP), HOMA-β, or 1,5-anhydroglucitol." (PMID 30943275, 2019). "In patients with AD, insulin signaling was found to be de-sensitized in the brain, even if they did not have diabetes." (PMID 31068799, 2019). "Shorter duration of diabetes, non-smoking status, absence of DFUs and non-use of insulin were found to be significant predictors of better HRQOL relating to energy and mobility." (PMID 31796044, 2019). "Diabetic ketoacidosis (DKA) is a serious metabolic state due to lack of insulin, and it is usually seen among patients with type 1 diabetes mellitus." (PMID 31101104, 2019). "Against this background, the present meta‐analysis aimed to systematically review and analyze the safety of Ramadan fasting among patients with type 1 diabetes mellitus who were treated with either the CSII or non‐CSII (including MDI and premixed insulin) regimen." (PMID 30938074, 2019). "As a medicine to treat diabetes, a noncommunicable disease, insulin stands out because, despite having been discovered in 1921 and first administered to an individual in 1922, access remains problematic." (PMID 31551632, 2019). "A 52-week double-blind placebo-controlled study in 136 obese patients with type-2 diabetes mellitus (T2DM) and metabolic syndrome analyzed various parameters, including: Fasting blood glucose, insulin, total cholesterol, HDL, LDL, triglycerides, and body mass index (BMI)." (PMID 31652576, 2019). "Medication use, in particular oral blood-glucose-lowering agents and/or insulin, can validate self-reported diagnosis of type 2 diabetes, or even ascertain the presence of diabetes when a participant does not report diabetes correctly in the questionnaire." (PMID 30460578, 2019). "The T2D groups were on medication for diabetes but the PCOS groups were not on any form of insulin control medication." (PMID 31456040, 2019). "Hemoglobin A1c did not strengthen the prediction algorithm of diabetes, determined by our proposed biomarkers, leptin, adiponectin, and insulin." (PMID 31379415, 2019). "Diabetes belongs to a group of metabolic disorders characterized by long term high blood glucose levels due to either inadequate production of insulin (Type 1 diabetes, T1DM) or poor response of the recipient cell to insulin (Type 2 diabetes, T2DM)." (PMID 31398847, 2019). "It is well established that type 2 diabetes mellitus (T2DM) generally results from the progressive failure of β-cell function, followed by a reduction in insulin secretion, which may actually aggravate the disease." (PMID 31018587, 2019). "In some rare cases (very poor metabolic control and/or self-control and/or cooperation with diabetes team, etc.)insulin pump therapy does not improve quality of life and metabolic control and should be replaced by pen therapy with fixed doses of insulin." (PMID 31183368, 2019). "The positive association of HbA1c and HOMA-IR suggests chronic mild hyperglycemia and decreased sensitivity to insulin is present even in the absence of overt diabetes in those with mild-moderate CKD." (PMID 30786864, 2019). "Diabetes is a disease that results from abnormal levels of insulin in the body, due to either a malfunction of the pancreas not producing enough insulin or the cells in the body not using it adequately." (PMID 30781431, 2019). "During the 90 days prior to starting insulin, participants used an average of 1.24 (SD = 0.54) non-insulin diabetes medications." (PMID 30759121, 2019). "The rate of the primary composite outcome was 6.3 per 100 patient‐years in patients without diabetes, and 10.2 and 17.1 per 100 patient‐years in diabetes patients without and with insulin use, respectively." (PMID 31271255, 2019).
diabetes (continued). "Rosiglitazone (RSG) is a kind of peroxisome proliferator-activated receptor-gamma (PPAR-γ) agonist, commonly used to treat type 2 diabetes mellitus (T2DM), which could enhance insulin sensitivity (Hiatt, Kaul & Smith, 2013)." (PMID 31637120, 2019). "Although the initial and quite reasonable hope was that leptin would become as dramatic a treatment of obesity as insulin was for diabetes, this has not proven to be the case." (PMID 30357355, 2019). "The results showed that 1,160(56.87%) adult patients with diabetes were taking antihyperglycemic medical treatments, out of which 240(21.14%) individuals administered insulin with or without using oral agents concurrently." (PMID 31461470, 2019). "The protein-tyrosine phosphatase 1B (PTP1B), a reticular non-transmembrane enzyme, has been validated as therapeutic target for diabetes, obesity, and breast cancer, due to its role as negative regulator of insulin and leptin signaling." (PMID 30875980, 2019). "Type 2 diabetes mellitus often develops due to obesity and lack of physical activity, which results in insulin resistance and can lead to decreased production of endogenous insulin as the disease progresses." (PMID 31781665, 2019). "Among women without diabetes (defined by self-report or insulin use) at the NHANES examination, 67.1% reported having had a diabetes screening test at least once in the past 3 years." (PMID 31651379, 2019). "Type 2 Diabetes Mellitus (T2DM), a metabolic disease characterized by chronic hyperglycemia, altered insulin secretion, and impaired glucose tolerance, occurs as a result of insulin resistance and the inability of the pancreas to increase insulin production in the event of hyperglycaemia." (PMID 31560710, 2019). "In 33 (13%) patients, class 4–5 variants were identified in one of four genes usually considered as rarely involved in monogenic diabetes in adults, namely HNF1B (15 cases, 6.0%, among which 10 HNF1B whole-gene deletion), ABCC8 (8 cases, 3.2%), KCNJ11 (3 cases, 1.2%), and INS (7 cases, 2.8%)." (PMID 31291970, 2019). "There are three main types of diabetes pathogeneses: Type 1 diabetes, also known as insulin-dependent, in which the pancreas fails to produce insulin, which is essential for survival." (PMID 31266160, 2019). "Diabetes mellitus is a chronic metabolic disease that is characterized by a relative lack of insulin, resulting in hyperglycemia." (PMID 30823474, 2019). "Marketed oral and injectable non-insulin antidiabetic agents have been demonstrated to be effective but they possess several adverse effects that contribute to consider the diabetes treatment approach with no adverse effects a challenge." (PMID 31658729, 2019). "Although β-cell mass diminishes in diabetes, it is not sufficient to account for the extent of reduction in insulin secretion." (PMID 31171772, 2019). "Other characteristics reported by one or two studies, were therequirement of high daily insulin dose to control blood glucose and lack of family history of diabetes." (PMID 31673335, 2019). "The postyield energy was not significantly different among the groups and was not significantly affected by diabetes status, insulin therapy or swimming training." (PMID 31038563, 2019). "Pioglitazone is used as an adjunct to diet, exercise, and other diabetes medications (e.g., glimepiride, metformin, and alogliptin) to manage type 2 diabetes by stimulating the nuclear receptor PPAR-γ, promoting insulin sensitivity and improving the uptake of blood glucose." (PMID 31699147, 2019). "Wall thickness, left ventricular mass and the proportion of participants with left ventricular hypertrophy was higher among those with diabetes not taking insulin than in those without diabetes and highest in those with diabetes treated with insulin." (PMID 31271255, 2019).
diabetes (continued). "Subsequently, we compared patients whose last filled prescription prior to insulin initiation was a single-compound non-insulin medication to those who were using multiple non-insulin diabetes medications." (PMID 30759121, 2019). "Diabetes is a rapidly growing public health problem worldwide, which is characterized by prolonged hyperglycemia and impaired insulin secretion together with or without insulin resistance." (PMID 30744071, 2019). "Diabetes can be split into two major subtypes; type 1 diabetes (T1DM), where an autoimmune response raised against the pancreatic β-cells impairs insulin production, and type 2 diabetes (T2DM) which is characterised by insulin resistance and often succeeded by β-cell dysfunction." (PMID 31798462, 2019). "A better management of diabetes mellitus requires determining the level of patient adherence and identifying why non-adherence to insulin therapy occurs." (PMID 31692777, 2019). "Diabetes mellitus (DM) is specifically characterized by a moderate or absolute lack of insulin, leading to hyperglycemia." (PMID 31597283, 2019). "Namely, that majority of patients continued non-insulin diabetes medications after insulin initiation, with differences across drug classes in the proportion being continued but the level of continued use differs across therapeutic drug classes." (PMID 30759121, 2019). "Among pregnancies in women without pre-existing diabetes, sulfonylureas (particularly glyburide) and insulin were the most commonly used products to treat gestational diabetes." (PMID 31775682, 2019). "These trials suggest that improving insulin sensitivity, one of the main effects of the (PPAR-γ) agonists, may not only reduce cardiovascular complications in patients with established diabetes but also in those in a pre-disease state." (PMID 30805659, 2019). "Although insulin is anabolic to bone and can restore markers of bone turnover and BMD, systematic review have identified no significant fracture reducing the potential for individuals living with diabetes mellitus on insulin treatment." (PMID 31575077, 2019). "The primary aim was to assess the relationship between DNA methylation at the KCNQ1 locus and measures of insulin sensitivity and β-cell function in a cohort of healthy individuals without diabetes." (PMID 30641161, 2019). "As the insulin signaling pathway controls the transport of glucose in hepatic cells, the dysregulation of IRS/AKT/GSK-3β insulin signaling pathway is a key determinant of the glycemic response showed in uncontrolled diabetes." (PMID 31442295, 2019). "In developing world, insulin therapy is not started earlier enough to achieve target glycemic goals to prevent complications of diabetes." (PMID 30881393, 2019). "Eligibility for IC requires good glycaemic control, no rapid insulin, no kidney failure and no diabetes complications." (PMID 31329611, 2019). "The analysis of the previous medication revealed similar pattern the drugs used related to diabetes (oral hypoglycemic agents or insulin), while none of the investigated subjects used any cardiovascular drugs." (PMID 31159858, 2019). "Significantly, insulin and demographic features do not provide additional performance improvement for diabetes prediction." (PMID 31826018, 2019). "However, our groups were matched for age, sex, diabetes duration, insurance range, CCI score, and medications (i.e., insulin, sulfonylurea, metformin, and glucobay) for the same observation period." (PMID 30813549, 2019). "Induction of diabetes and administration of troxerutin and insulin did not change the TAC level significantly compared to the C group." (PMID 30834086, 2019). "Diabetes mellitus (DBM) is a chronic disease that arises either when the pancreas does not produce enough insulin, or when the body cannot efficiently use the insulin it produces." (PMID 31652912, 2019).
diabetes (continued). "Patients with LLA had lower rates of statins, antiplatelet therapy, ACE inhibitors and Angiotensin Receptor Blockers, metformin and insulin prescriptions at baseline compared to those without diabetes-related LLA (p < 0.001)." (PMID 30823912, 2019). "Patients with diabetes show problems with glucose utilization and metabolism due to a lack of insulin secretion." (PMID 31640118, 2019). "No judge would prohibit a patient suffering from diabetes from using insulin and instead impose a diet and physical training on him because he does not believe in the effect of the approved drugs against diabetes." (PMID 31864356, 2019). "GIP administration, even at higher than normal physiological doses, did not stimulate insulin secretion in diabetic humans, indicating that diabetes in some way interferes with GIP signaling." (PMID 31687648, 2019). "Another study found that baseline sCD36 did not predict diabetes independently of fasting glucose and insulin in a non-diabetic population." (PMID 31109109, 2019). "In healthy individuals, the mean serum insulin AUC was 109.7 ± 19.7 mU * h/L, not significantly different from the two diabetes groups." (PMID 31119456, 2019). "In the context of diabetes, one feature of such ‘stunned’ cells, is that there is not only a mismatch between insulin secretion and glucose stimulus, but also that the change can recover." (PMID 31558146, 2019). "Those who achieved diabetes remission at 8 weeks were slightly younger and had significantly higher fasting insulin and C‐peptide at baseline compared to those who did not achieve diabetes remission." (PMID 30918654, 2019). "Secondly, The DKT asks 9 questions about insulin, the study sample did not use insulin to manage their diabetes and the intervention had no education on insulin." (PMID 31516728, 2019). "In the current study, both BP and MTS significantly elevated the serum OCN and bone-ALP levels that were lowered by diabetes; however, they did not affect blood glucose, HbA1c or serum insulin level when compared to the DM group." (PMID 30875838, 2019). "The following variables that were significant in the univariate analysis were included in the prediction model: presence or absence of DFU, income, duration of diabetes, use of insulin only, use of a combination of insulin and oral medications, and BMI." (PMID 31796044, 2019). "Diabetes mellitus describes a group of metabolic diseases in which the patient has high blood glucose (blood sugar), either because insulin production is inadequate, or because the body’s cells do not respond properly to insulin, or both." (PMID 30769799, 2019). "First, this study did not stratified diabetes mellitus according to its different types (insulin-dependent, noninsulin-dependent, neonatal) to identify which has greater relation with physical inactivity." (PMID 30867683, 2019). "A systematic review has shown that BMI, family history of diabetes, non-white ethnicity, advanced maternal age, early diagnosis of GDM, raised FPG and HbA1c, and insulin use during pregnancy are associated with future risk of T2DM." (PMID 30893935, 2019). "Higher cumulative costs of BITA compared with SITA at 5 years were found to be particularly marked in patients who were insulin-dependent compared with those who were non-insulin dependent or were without diabetes." (PMID 30948516, 2019). "The accurate pathophysiology of cognitive dysfunction in diabetes is not totally defined, but probably hyperglycemia, vascular disease, hypoglycemia events, and insulin resistance are the main factors." (PMID 31284568, 2019). "We investigated irisin correlation with bone status in 96 children diagnosed with childhood type 1 diabetes mellitus (T1DM), further divided with 56 children receiving multiple insulin daily injections (MDI) and 40 children on continuous subcutaneous insulin infusion (CSII)." (PMID 31091695, 2019).